CD47 (CD47 molecule)
Diseases named in the same sentence as CD47 in open-access papers (continued):
Sharing a sentence is not in itself a finding about the gene and the disease.
lung squamous cell carcinoma (5 papers, 2022 to 2025). "The Clinical Proteomic Tumor Analysis Consortium (CPTAC) suggests that the expression of TRAF2 is significantly positive correlated with CD47 protein levels in lung squamous cell carcinoma (LUSC) among 12 types of tumor." (PMID 39665172, 2025). "For example, patients with M1 stage lung squamous cell carcinoma malignancy expressed more CD47 than patients with M0 stage." (PMID 38720108, 2024).
lymphopenia (5 papers, 2021 to 2022). Reduction in the number of lymphocytes. "While IFN activated monocytes with increased CD47 expression might still provide enough inhibitory signaling, lymphocytes such as T and B cells without CD47 upregulation might be more susceptible to removal by activated monocytes/macrophages which could lead to common lymphopenia in SLE patients." (PMID 34068752, 2021). "In the context of the toxicities generated by blockade of the SIRPα-CD47 checkpoint in cancer therapies, we sought to address the role of PMN in the lymphopenia observed with anti-CD47 antibody treatment." (PMID 35795660, 2022). "Despite their promising pre-clinical results, the clinical progress of anti-CD47 mAb therapies have been limited by on-target, non-tumor toxicities including anemia, neutropenia, thrombocytopenia, and lymphopenia." (PMID 35795660, 2022). "Although lymphopenia was observed in peripheral blood of approximately 35% Hu5F9-G4-treated patients it remains unclear whether CD4+ and CD8+ tumor-infiltrating T cells are impacted by prolonged anti-CD47 treatments." (PMID 35664753, 2022).
mycosis fungoides (5 papers, 2020 to 2026). Classical mycosis fungoides is the most common type of mycosis fungoides (MF), a form of cutaneous T-cell lymphoma, and is characterized by slow progression from patches to more infiltrated plaques and eventually to tumors. "Malignant lymphocytes of mycosis fungoides and Sézary syndrome express CD47 highly, thus, being ideal candidates for targeted anti-CD47 therapies." (PMID 36429020, 2022). "Collectively, these findings support CD47 as a therapeutic target in treating mycosis fungoides and demonstrate a synergistic role of interferon-α in exploiting these clinical benefits." (PMID 34885092, 2021). "Furthermore, we have demonstrated that novel anti-CD47 immunotherapy with mycosis fungoides leads to the reduction of exhausted T cells accompanied by the expansion of NK and CD8+ T cells." (PMID 34885092, 2021). "Thus, we showed that CD47 might serve as an effective therapeutic target in treating mycosis fungoides." (PMID 34885092, 2021). "Materials and Methods: This retrospective study evaluated the immunohistochemical expression of CD47, CD163, and B7-H3 in 46 patients with early-stage mycosis fungoides (MF) and 46 patients with large plaque parapsoriasis (LPP)." (PMID 42075550, 2026).
nasopharyngeal carcinoma (5 papers, 2020 to 2025). A carcinoma arising from the nasopharyngeal epithelium. "MicroRNA 200a suppressed nasopharyngeal carcinoma (NPC) cell proliferation, migration, and invasion, and promoted phagocytosis of NPC cells by macrophages through down-regulation of CD47 expression on NPC cells." (PMID 35418166, 2022). "In nasopharyngeal carcinoma (NPC), the coinhibition of miR-200a and CD47 exerts a more potent inhibition of tumor proliferation than the single-block group, but the specific mechanism has not been elucidated clearly." (PMID 36358792, 2022).
pancreatic neuroendocrine tumor (5 papers, 2021 to 2025). Pancreatic endocrine tumor, also known as pancreatic neuroendocrine tumor (PNET), describes a group of endocrine tumors originating in the pancreas that are usually indolent and benign, but may have the potential to be malignant. "Tumor cells express CD47 to recede from macrophage engulfment, and low CD47 expression is favorable for tumor progression in pancreatic NETs." (PMID 35740577, 2022). "However, the clinical significance of CD47 expression and CD163+ TAMs in pancreatic neuroendocrine tumor (PanNET) remains unclear." (PMID 33765961, 2021).
serous ovarian carcinoma (5 papers, 2017 to 2024). "It has been reported that CD47 is amplified in 15/316 (5%) of TCGA ovarian serous carcinomas." (PMID 38832992, 2024). "The anti-tumor activity of the anti-CD47 blocking antibody, Hu-5F9, was assessed (compared to control and to Olaparib) in a PDX model of chemotherapy resistant, PARP inhibitor resistant high grade serous ovarian cancer." (PMID 37468567, 2023).
Splenomegaly (5 papers, 2019 to 2024). Abnormal increased size of the spleen. "However, CD47 can be also found on red blood cells which can lead to splenomegaly when targeted therapy against CD47 is used." (PMID 38892394, 2024). "Besides, the significant increase of the spleen weight of mice treated with Hu5F9 is consistent with the commonly observed splenomegaly in hemolytic anemia due to accumulation of macrophages and CD47−/− RBCs in mice." (PMID 36650558, 2023). "Finally, we demonstrate that anti-CD47 (MIAP410) causes splenomegaly and activation of DCs and T cells, without affecting NK cell activation." (PMID 31337788, 2019). "PV mice developed pronounced splenomegaly, which was not affected by CD47-SIRPα blockade at 2 and 4 weeks in PV mice." (PMID 37095207, 2023). "In addition, and as expected, benchmark experiments revealed that TAX2 peptide does not recapitulate adverse events relative to anti-CD47 therapies, especially regarding splenomegaly, hematology, red blood cells count, necrosis, hemoglobin concentration, platelets count and leukocyte count." (PMID 34638503, 2021).
systemic lupus erythematosus (5 papers, 2021 to 2025). An autoimmune multi-organ disease typically associated with vasculopathy and autoantibody production. "In a murine lupus model, CD47 deficiency improves autoimmune nephritis by suppressing IgG autoantibody production." (PMID 34068752, 2021). "Indeed, CD47 deficiency ameliorates autoimmune nephritis in Fas (lpr) murine lupus model and experimental autoimmune encephalitis." (PMID 34068752, 2021). "Plus, individuals with systemic lupus erythematosus had circulating natural CD47 autoantibodies, while the level of immune cell CD47 correlated with the severity of inflammation." (PMID 41511354, 2025). "In contrast, blocking with anti-CD47 mAb in lupus or EAE with active phase worsens the disease activity." (PMID 37368493, 2023). "CD47 KO in Faslpr lupus mice reduces autoantibodies and protects mice against lupus." (PMID 37368493, 2023). "However, blocking CD47 at the peak of the disease worsens disease activity in mouse models of systemic lupus erythematosus (SLE) and experimental autoimmune encephalomyelitis (EAE)." (PMID 37781373, 2023). "A potential candidate factor in SLE serum for CD47 induction is IFN-α, a key cytokine in SLE, which is increased in the tissue and blood of patients during a lupus flare." (PMID 34068752, 2021). "In autoimmune conditions, including systemic lupus erythematosus (SLE), central nervous system autoimmunity, and autoimmune vasculitis, CD47 overexpression exacerbates inflammation, while blockade enhances efferocytosis and promotes immune resolution, thereby attenuating disease severity." (PMID 41303525, 2025). "Considering that contradictory effects of CD47 blockade, presumably due to the macrophage activation, have been reported in lupus and EAE mouse models, further studies are needed to assess the therapeutic effects of anti-CD47 mAb in AAV mouse models with active disease." (PMID 37368493, 2023).
type 2 diabetes (5 papers, 2012 to 2025). "We also found concurrent upregulated expression of CD47 and senescence markers in the endocrine pancreas of aged donors and those with type 2 diabetes." (PMID 40133488, 2025). "We measured elevated CD47 mRNA levels both in the hippocampus and in the prefrontal cortex of type 2 diabetes model animals, providing a plausible link between central insulin resistance and Alzheimer-type neurodegeneration." (PMID 22369239, 2012). "The CD47 gene that is a negative modulator of insulin receptor activation and associated with type II diabetes mellitus development, was identified as a direct target of miR‐708." (PMID 31273952, 2019). "Interestingly, metformin reduces the stem cells through miR‐708 mediated repression of the gene CD47, which is involved in type II diabetes development." (PMID 31273952, 2019). "In addition, the anti‐type II diabetes drug metformin are found to be involved in the miR‐708/CD47 signalling pathway." (PMID 31273952, 2019).
Arthritis (4 papers, 2010 to 2025). Inflammation of a joint. "Next, we locally injected into CIA rats the CD47 antibody or inhibitors of key pathways in which CD47 activated integrin α4β1 (phosphorylating the α4 subunit cytoplastic domain) in T cells, and examined their effects on arthritis development." (PMID 40308591, 2025). "Starting from this, we aim to investigate and answer the following questions: Which immune cell surface CD47 interacts with TSP-1 on the vascular wall of arthritis rat synovial tissue?" (PMID 40308591, 2025). "Cd47 knockout rats were included in CIA model here to explore the potential and critical role of CD47 in arthritis development." (PMID 40308591, 2025). "Specifically, we identified key enzymes in the intracellular signaling pathway of T cells through which CD47 activates integrin α4β1 to verify whether inhibiting the activity of these key enzymes would affect arthritis development." (PMID 40308591, 2025). "Thus, Cd47 knockout could mitigate the severity of arthritis by reducing the infiltration of T cells (especially Th17 cells) into articular synovial tissues." (PMID 40308591, 2025). "This not only demonstrates the establishment of the proposed three-molecule model of “TSP-1, CD47, and integrin α4β1” in collagen-induced arthritis at the whole animal level, but also suggests that the interaction among these three molecules plays an important role in collagen-induced arthritis." (PMID 40308591, 2025). "It was further observed that subcutaneous injection of CD47 antibodies or inhibitors of PKA and Src kinases into the left hind paw of wild-type rats effectively alleviated arthritis symptoms." (PMID 40308591, 2025). "When Cd47 was knocked out in a rat CIA model, the disease severity of arthritis was significantly alleviated, and the T cell infiltration into rat synovial tissue was remarkably reduced, while the number of B cells, macrophages, and neutrophils did not noticeably change." (PMID 40308591, 2025). "Compared with the WT-CIA group, the CD47-KO-CIA group exhibited significant decreases in the swelling of the left and right hind paws, arthritis and clinical scores, as well as levels of rheumatoid factor (RF), TNF-α, total leukocytes, neutrophils, and platelets in the blood." (PMID 40308591, 2025).
breast invasive carcinoma (4 papers, 2019 to 2025). "Two hundred seventeen cases of primary invasive breast cancer and 40 cases of benign breast lesions were collected to examine the expression level of CD47 protein by IHC staining." (PMID 31528120, 2019). "Normal breast tissue similarly lacked the positive correlation between CD47 and SLFN11 observed in invasive breast carcinomas." (PMID 31632920, 2019).
chordoma (4 papers, 2020 to 2023). Chordomas are rare malignant tumors arising from embryonic remnants of the notochord in axial skeleton. "Among STS, CD47 expression appears bimodal, with the highest protein expression level observed in chordoma, angiosarcoma, and pleomorphic liposarcoma; CD47-expressing tumors are associated with worse OS than are CD47-negative tumors." (PMID 37046760, 2023). "The expression of the macrophage-related immune checkpoint CD47/SIRP was also extremely high in chordoma, with CD47 expressed on all tumor cells in 82% of cases, and SIRP+ macrophage infiltration present in 71% of cases." (PMID 37720221, 2023). "For instance, infiltrating macrophages in chordomas are predominantly M2 (anti-inflammatory) macrophages; elevated CD47 expression on chordoma cells also downregulates pro-inflammatory macrophage activity." (PMID 32733369, 2020). "Furthermore, CD47 was correlated with SIRPα score, with the highest expression observed in chordoma, angiosarcoma, and pleomorphic liposarcoma." (PMID 36900335, 2023). "A variety of immunosuppressive checkpoints such as PD-1/PD-L1, CD47/SIRPα, TIM3, and CTLA4 are expressed on the surface of both chordoma cells and immune cells, and ICIs are the most widely performed strategy in the field of chordoma immunotherapy." (PMID 37720221, 2023).
colorectal tumor (4 papers, 2019 to 2025). "Analysis of single-cell sequencing data of human and mouse colorectal tumor tissues revealed elevated CD47 expression on myeloid cells and the expression of PD-L1 expressed on various immune cells." (PMID 38462636, 2024).
cutaneous melanoma (4 papers, 2020 to 2024). A primary melanoma arising from atypical melanocytes in the skin. "In contrast, higher CD47 expression in cutaneous melanomas is associated with increased overall and disease-free survival and increased tumor infiltration and activation of NK and CD8 T cells." (PMID 39201643, 2024). "In contrast, elevated CD47 expression in cutaneous melanomas is associated with improved survival." (PMID 36768931, 2023). "Analysis of TCGA RNAseq data from cutaneous melanomas established that mRNAs encoding the CD8 T cell coreceptor subunits CD8α and CD8β have strong positive correlations with CD47 mRNA expression." (PMID 36768931, 2023). "Correspondingly, CD47 was ranked 432nd for coexpression with IFT57 in cutaneous melanoma." (PMID 39201643, 2024). "Cutaneous melanomas exhibit a strong positive correlation between CD47 mRNA expression and improved survival, which relates to enhanced NK and CD8 T cell activation in tumors with elevated CD47." (PMID 39201643, 2024). "In addition, the expression of CD47 was positively correlated with ZEB1 in 178 PDAC and 103 skin cutaneous melanoma (SKCM) patients." (PMID 32536914, 2020).
endometriosis (4 papers, 2023 to 2025). The growth of functional endometrial tissue in anatomic sites outside the uterine body. "Dysregulation of key ICP pathways, such as PD-1/PD-L1, TIM-3/Gal-9, CTLA-4/CD80/CD86, and CD47/SIRPα, has been documented in endometriosis." (PMID 40679648, 2025). "In endometriosis, the lesional staining of CD47 is indeed elevated and reduces the phagocytosis efficiency of macrophages on endometriotic stromal cells." (PMID 36769489, 2023). "CD47-SIRP-α) is considered a macrophage-associated immune checkpoint, and the expression of CD47 is increased in the peritoneal cavities of patients with endometriosis." (PMID 36865552, 2023). "In addition, TSP-1/CD47/SIRPα collectively enhance cellular viability, reduce apoptosis, and facilitate fibrosis, as in endometriosis." (PMID 36769489, 2023).
Ewing sarcoma (4 papers, 2020 to 2025). A small round cell tumor that lacks morphologic, immunohistochemical, and electron microscopic evidence of neuroectodermal differentiation. "In Ewing sarcoma (ES), we found that tumor cells utilize dual mechanisms to evade macrophage clearance by simultaneously over-expressing CD47 and down-regulating cell surface calreticulin (csCRT), the pro-phagocytic signal." (PMID 38992659, 2024).
pneumonia (4 papers, 2018 to 2025). An acute, acute and chronic, or chronic inflammation focally or diffusely affecting the lung parenchyma, caused by an infection in one or both of the lungs (by bacteria, viruses, fungi, or mycoplasma.). "The results showed that adherence of pneumonia-causing gram-positive bacteria S. aureus and S. pneumoniae to cellular CD47 was significantly inhibited following pre-incubation of the cells with α-hCD47 antibodies." (PMID 38693120, 2024). "In our preliminary study, designed to elucidate the mechanistic basis how bacteria causing pneumonia following a secondary bacterial infection bind to CD47, we examined whether other pneumonia-causing bacteria bind to CD47." (PMID 38693120, 2024). "The expression of CD47 in cluster 03 significantly increased in CD3+ T cells of patients with stable pneumonia." (PMID 34841705, 2021). "Compared to the uninfected group, S. pneumoniae lung infection in general significantly increased CD47 expression in lung neutrophils, and to a lesser extent in splenic neutrophils." (PMID 29755958, 2018). "Vitamin E may also help prevent infection as high-dose administration has shown to increase levels of anti-inflammatory CD47 and allow for shorter hospitalization times in patients with pneumonia." (PMID 41459083, 2025).
rheumatoid arthritis (4 papers, 2015 to 2025). A chronic, systemic autoimmune disorder characterized by inflammation in the synovial membranes and articular surfaces. "The three-molecule model of “TSP-1, CD47 and integrin α4β1” confirmed that CD47 plays an important role in the occurrence and progression of collagen-induced arthritis, a typical animal model of rheumatoid arthritis." (PMID 40308591, 2025). "Based on the results of GEO data analysis and with Jurkat cells, the three-molecule model may also explain the important role of CD47 in rheumatoid arthritis." (PMID 40308591, 2025). "Blocking the TSP-1-CD47 interaction or inhibiting CD47-activated integrin α4β1 on T cells could be a potential therapeutic strategy for rheumatoid arthritis." (PMID 40308591, 2025). "This study proposes a three-molecule model of “TSP-1, CD47 and integrin α4β1” to confirm that CD47 plays an important role in the occurrence and progression of collagen-induced arthritis, a typical animal model of rheumatoid arthritis." (PMID 40308591, 2025). "In the analysis of clinical samples from the GEO database, we found that CD47, its ligand TSP-1, several integrin subunits (α4, αm, αL, αv, β1, β2, β3) were significantly overexpressed in the synovial tissue of patients with rheumatoid arthritis." (PMID 40308591, 2025). "This suggests that monoclonal antibodies against CD47 (if their side effects can be resolved), as well as inhibitors of PKA kinases and Src kinases, particularly specific inhibitors of Src kinase, may reduce T cell infiltration into inflammatory sites and thereby treat rheumatoid arthritis." (PMID 40308591, 2025). "Based on information from the Cortellis platform Drug Discovery Intelligence, there are currently no CD47 antibodies, PKA inhibitors, or Src inhibitors used to treat rheumatoid arthritis." (PMID 40308591, 2025). "Indeed, exposure to IFN-α increased CD47 expression on monocytes, whereas TNF-α, a major cytokine produced during inflammatory responses to bacterial infections and rheumatoid arthritis, did not." (PMID 34068752, 2021).